CD163 (CD163 molecule)
Diseases named in the same sentence as CD163 in open-access papers (continued):
Sharing a sentence is not in itself a finding about the gene and the disease.
infection (continued). "From this point of view, the pig is completely different because the CD14low/CD163+ “steady-state” monocytes are replaced by the phenotypically distinct “inflammatory” subset during APP infection." (PMID 24134635, 2013). "For CD163, IL-10 inducing strains were able to keep the proportions of double positive SLAII/CD163 cells compared to mock-inoculated culture cells while infection with a IL-10-/TNF- strain (3267) produced a clear decline of double positive SLAII/CD163 cells." (PMID 21314968, 2011). "In this study, cell lines that express both recombinant Sn and CD163 (CHOSn-CD163 and PK15Sn-CD163) were made, as both receptors are involved in infection of the natural host cell, the macrophage." (PMID 20587060, 2010). "Treatment of the cells with neuraminidase before inoculation enhanced the infection rate of PK15Sn-CD163 cells." (PMID 20587060, 2010). "After treatment of the cells with neuraminidase, infection with macrophage grown virus increased on PK15Sn-CD163 cells." (PMID 20587060, 2010). "Macrophage grown virus gave little infection, but if the cells were first treated with neuraminidase, infection was slightly better in the case of PK15Sn-CD163 cells." (PMID 20587060, 2010). "The difference in isolation efficiency between Marc-145 cells and macrophages is suggesting that another receptor next to CD163 is involved in infection as Marc-145 cells and macrophages both express CD163." (PMID 20587060, 2010). "For PK15Sn-CD163 cells, the infection rate for Marc-145 grown LV as well as VR-2332 was approximately 80%, independently of densities and cultivation time." (PMID 20587060, 2010). "Since the interaction between sialic acids on PRRSV and sialoadhesin is important for infection of cells, desialylation of the CHOSn-CD163 and PK15Sn-CD163 cells can probably enhance the amount of infected cells by macrophage grown virus." (PMID 20587060, 2010). "The results showed that treatment of the PK15Sn-CD163 cells at 200 000 cell/mL with neuraminidase before inoculation enhanced infection of the cells with macrophage grown virus." (PMID 20587060, 2010). "The dramatic reduction in Cd163 expression occurred before any other inflammatory markers, except the serum amyloid genes, had responded to infection." (PMID 19365556, 2009). "A greaternumber of neonates and children is needed for a more precise evaluation of diagnosticaccuracies of selected infection markers (CD64 and CD163 index for monocytesand neutrophils) and for comparison with routinely used infection markers inthe future." (PMID 18604302, 2008). "Evaluation of the expression of macrophage cell markers with levels of ASFV infection in PBMCs also revealed that CD45+ and MHCII+ cells are strongly associated with infection, while CD163+ and CD203a+ expression is non-essential." (PMID 40692871, 2025). "Four major features characterized these cells: 1) a dominant CD163-expressing population that emerges during acute infection before dissipating, 2) a major source of CXCL10 expression, 3) a high enrichment in viral RNA, and 4) the induction of robust antiviral responses." (PMID 40920821, 2025). "In conjunction with infection, we observed elevated expression of CD163 in the BRN, KID and LNG of HV-MEC fetuses which could be explained by three distinct hypotheses." (PMID 38389522, 2024). "Based on all the described observations, we conclude that pigs with the SRCR5 domain removed from CD163 protein are not different from the control pigs, except for the resistance to the infection caused by the PRRS virus." (PMID 38544785, 2024). "Additionally, cells with higher levels of CD163 require larger quantities of anti-CD163 antibodies to achieve complete infection blockade." (PMID 39723134, 2024). "However, the reduction in infection was more pronounced in PAMs than in PPMs although PAMs and PPMs were treated with the same amount of anti-CD163 antibodies." (PMID 39723134, 2024).
infection (continued). "Several studies have reported that CD163 expression confers susceptibility to PRRSV; however, there may be differences depending on the PRRSV strain and infection titer." (PMID 39776598, 2024). "Future work quantifying CD163 expression in the liver in addition to CD68 over the course of the infection in the cynomolgus macaque model used in this study would help clarify if the same pattern is present in both models or if these represent distinct immunologic responses." (PMID 39635525, 2024). "In summary, pigs with modified CD163 protein are not different from the control pigs, except for the resistance to the infection caused by the PRRS virus." (PMID 38544785, 2024). "Another study revealed that the mRNA level of CD163 in PAMs of Dingyuan pigs is significantly lower than that of Jiangquhai pigs within 24 h post-infection (hpi); this may account for the high resistance of Jiangquhai pigs to PRRSV." (PMID 37929286, 2023). "We should not totally exclude certain roles of other peptides within CD163 in mediating infection, especially the interaction between CD163 and the virulence factors of G. parasuis, although based on previous reports and our investigation, we presume that this possibility is very low." (PMID 36977274, 2023). "Interestingly, the PRRSV infection led to a significant decrease in the population of CD163+ and other markers of PAMs, suggesting that the cells were targeted for infection or killed by the virus." (PMID 36992483, 2023). "We therefore examined the percentage of CCR5+ CD163 cells across stages of infection." (PMID 37366075, 2023). "Consequently, PRRSV adopts an alternative route of infection via macrophage activity involving CD163." (PMID 37929286, 2023). "The expression of CD163 gradually increased with the prolongation of infection time." (PMID 36169259, 2022). "Concerning CD163, an increase in its expression was observed on D5 compared to D3 in both monocyte subpopulations found in the spleen, suggesting increased removal of hemoglobin/haptoglobin complexes at this point during infection." (PMID 36310859, 2022). "CD163 is a scavenger receptor for haptoglobin/hemoglobin complex, considering its scavenging properties, it is possible that its downregulation by S27 contributes to release of heme-derived iron to support pathogen growth and infection." (PMID 35387075, 2022). "ASFV infected macrophages had an enhanced expression of CD163 and anti-CD163 antibodies could block infection of ASFV in macrophages in a dose dependent manner." (PMID 35755158, 2022). "Comparison of sTREM-1, CD163 and sTWEAK levels of different infection severity(X ̄±S)." (PMID 35480505, 2022). "CD163-3D4/21 cells were tested for infection with PRRSV R98 strain of lineage 5 at an MOI of 0.1." (PMID 36146862, 2022). "Additionally, among the co-cultures, a higher expression of CD163 was shown in the co-culture condition where the hMDMs were added after the infection." (PMID 36275746, 2022). "Interestingly, infection with 26544/OG10 led to a statistically significant downregulation of CD163 on all macrophage subsets." (PMID 35215110, 2022). "Interestingly, CD163 was strongly expressed by Ly6Chi monocytes in the brain before infection and until D3, repressed between D5 and in treated mice until D8, and finally restored on D12." (PMID 36310859, 2022). "CD163 gene knockout pigs display resistance to infection by the Georgia07 strain." (PMID 36389805, 2022). "Additionally, we noticed the large variations of different PRRSV2 strains during infections of CD163-3D4/21 cells versus MARC-145 cells." (PMID 36146862, 2022). "Duroc pigs with the deletion of CD163 gene are also not susceptible to infection by highly pathogenic PRRSV stain TP, indicating that PRRSV infection of different breeds of pigs is dependent on membrane CD163 receptor." (PMID 36187992, 2022). "Therefore, the CD163-3D4/21 cells were tested for infections by NADC30-like PRRSV2 strain SD17-38 and NADC34-like PRRSV2 strain Anheal-1." (PMID 36146862, 2022).
infection (continued). "The abilities of anti-Sn or CD163 antibodies to block infection enhancement in vitro might have important implications for preventing or decreasing the development of PRRS mediated by antibodies in PRRSV-infected pigs." (PMID 36136686, 2022). "Here, we observed that CD163-3D4/21 cells were able to support the infections of all tested PRRSV2 strains, including NADC30-like PRRSV (SD17-38) and NADC34-like PRRSV (Anheal-1), in spite of their failure to infect MARC-145 cells, which is the first report as far as we know." (PMID 36146862, 2022). "Additionally, the highest expression of CD163 (M2) was shown in the co-culture condition where the hMDMs were added after the infection (condition that showed a delay in the viral replication)." (PMID 36275746, 2022). "Pigs with a deletion of either full-length CD163 or the entire SRCR5 domain of CD163 or the partial SRCR5 domain including ligand binding pocket exhibit complete resistance to infection with PRRSV, indicating that CD163 SRCR5 domain is the binding site of the virus." (PMID 36187992, 2022). "Moreover, we measured alterations in protein expression around infected hepatocytes and identified a subset of CD163+ Kupffer cells that migrate towards infected cells during infection." (PMID 35111697, 2021). "Interestingly, an independent study in China showed that pigs with CD163 SRCR5 domain-swap with hCD163L1 SRCR8 were resistant to HP-PRRSV JXA1 infection." (PMID 33916997, 2021). "Interestingly, different strains of PRRSV show different infection preferences in PK-15 cells co-expressing siglec-1 and CD163, or siglec-10 and CD163." (PMID 33916997, 2021). "Scavenger receptor CD163 is considered as an indispensable mediator for PRRSV infection because CD163 expression in non-permissive cell lines makes them susceptible to PRRSV infection and CD163 knockout pigs are resistant to infection with PRRSV." (PMID 32093748, 2020). "Monocytes and macrophages from these pigs were also susceptible to infection confirming that CD163 is not required." (PMID 32515659, 2020). "For example, pigs with alterations in the CD163 gene are fully resistant to infection with PRRSV17." (PMID 32488046, 2020). "CD163 is an essential receptor for PRRSV during its infection of cells." (PMID 33251273, 2020). "As long as the infection lasted, the number of cells expressing CD163 grew." (PMID 31086416, 2019). "Taken together, CD163-edited cell lines 87 and 4 were resistant to infection with PRRSV-2 isolates." (PMID 32038556, 2019). "Finally, THC/SIV rhesus macaques had a significantly higher percentage of anti-inflammatory CD163+ macrophages in their intestines at 180 days post-infection." (PMID 31114576, 2019). "Infections were carried out with bacteria expressing green fluorescent protein (GFP) to assess CD163 levels in cells with and without associated bacteria." (PMID 31796543, 2019). "Previous studies have shown that macrophages with CD163 SRCR5 deletion derived from peripheral blood monocyte are not susceptible to infection with PRRSV-2." (PMID 32038556, 2019). "Additionally, another M2 phenotype analyzed as a double positive, CD206+/CD163+ cells, showed a clear tendency toward an increased percentage after infection with P strain as compared to Mock and C#1 strain infection (44.2 vs. 29.9% and 33.9%, respectively)." (PMID 31695702, 2019). "With the growth of CD163, the infection of PRRSV in cultured monocytes is regularly increasing." (PMID 29682543, 2018). "Also, we provide an immunohistochemistry analysis by probing the presence of the parasite and macrophages (L1 and CD163) during the early and later steps of the infection." (PMID 29896161, 2018). "PRRSV initiated efficient infection only in cells with high CD163 abundances." (PMID 29552301, 2018). "Positive selection on CD163 is consistent with its known role in infection." (PMID 30572815, 2018).
infection (continued). "Previous research found that the virus needs a specific receptor, CD163, in order to make its own membrane fuse with the host cell membrane in an uptake vesicle to release the viral genetic information into the cytosol and achieve a successful infection." (PMID 28231264, 2017). "Moreover, when macrophages were incubated with a specific anti-CD163 antibody, the levels of infection and viral binding decreased in a dose-dependent manner." (PMID 29117102, 2017). "PMMs from the different CD163 genotypes were subjected to a multiple-round infection." (PMID 28231264, 2017). "One conclusion from these studies was that CD163 may be necessary but insufficient for infection, suggesting that other macrophage surface proteins may participate in the infection process." (PMID 28489063, 2017). "In this view, our findings could also suggest that instead of a protective role, placental CD163+ cells may play a role in transplacental infection or viral replication in the fetal compartment following infection." (PMID 27494990, 2016). "Indeed, in experimental studies increased levels of infection are often correlated with increased expression of CD163." (PMID 27770812, 2016). "In this study we combine in-vitro and in-silico infection models to determine whether and how the susceptibility of cultured PAMs to PRRSV changes over time and to examine possible functional modulation of CD163." (PMID 27770812, 2016). "However, there was a positive correlation between the density of CD163 positive cells and infection burden in the 14 dpc group (correlation = 0.79), measured as L. intracellularis 16S rRNA copies per nanogram of total genomic DNA." (PMID 24885874, 2014). "This indicates that CD163 expression alone is not sufficient to increase ASFV infection in cells that are not susceptible to infection." (PMID 24398227, 2014). "This indicates that CD45+ and MHCII+ cells are strongly associated with infection and that CD163+ and CD203a+ cells can become infected but the expression of these markers is not necessary for infection." (PMID 24398227, 2014). "CD163 and CD203a expression correlated at intermediate levels with infection, indicating cells expressing these markers could become infected but were not preferentially infected by the virus." (PMID 24398227, 2014). "Experiments were carried out to determine if cell surface expression of CD163 either conferred susceptibility to infection with ASFV field isolates which usually do not infect stable cell lines without adaptation." (PMID 24398227, 2014). "The results using CD68 and CD163 indicate that following SIV infection expression levels are increased 43 weeks post SIVmacJ5 or SIVmacC8 challenge with the highest expression levels being found 23 weeks post SIVmac17E-Fr infection." (PMID 22403025, 2012). "Other studies have revealed that CD163 can be a macrophage receptor for the binding of bacteria and that it can promote bacteria-induced production of proinflammatory cytokines during infection." (PMID 21599948, 2011). "Both CHOSn-CD163 and PK15Sn-CD163 cells showed a low infection rate with macrophage grown virus." (PMID 20587060, 2010). "CD163 is also involved in infection of macrophages, probably at the stage of virus disassembly." (PMID 20587060, 2010). "In the current study Cd163 expression appeared to be an exquisitely sensitive marker of infection since expression declined >10 fold within three days of infection when parasites are hard to detect by microscopy and before any increase in expression of inflammatory cytokines." (PMID 19365556, 2009). "However, genetically modified pigs deficient in CD163 do not exhibit resistance to infection with the Georgia 2007/1 strain, suggesting that the host’s immune system and viral pathogenesis are more complex than previously assumed." (PMID 40008879, 2025).
infection (continued). "To determine whether myeloid cell recruitment accounted for the increased area of infection within the dermis, we first quantified the density of macrophages, identified by the expression of CD163, in skin inoculated in the absence or presence of mosquito probing." (PMID 39205228, 2024). "Interestingly, it has been revealed that porcine CD163 provides the infections of both European PRRSV (type 1) and North American PRRSV (type 2), whereas human CD163 supports only type 2, and whether type 1 is involved is not revealed." (PMID 39459897, 2024). "We found that IbAr10200-infected mice had significantly elevated plasma CD163 compared to uninfected normal C57BL/6 mice and Turkey04-infected mice at 3 dpi, supporting the finding that macrophage-associated inflammation early after infection corresponds with lethal outcome." (PMID 39513496, 2024). "Hence, the sole cAMP-elevating activity of the CyaA toxin strongly downregulated the M-CSF-triggered surface expression of the iron acquisition receptors CD71 and CD163 in M-CSF-differentiated monocytes also in the context of the infection by live B. pertussis bacteria at a very low MOI of 2:1." (PMID 39078132, 2024). "Subsequent analysis showed that the CD163+ subset had greater expression of other typical macrophage molecules compared to the CD163- subset, suggesting that these cells may perform different roles during infection." (PMID 38951667, 2024). "Furthermore, pretreatment of PPMs with an anti-CD163 antibody reduced the infection." (PMID 39723134, 2024). "For example, the CC genotype of CD163 at the C3534T polymorphism has been found to be significantly associated with low IgG levels after the PRRS challenge, while, on the other hand, the AA genotype of G2494A polymorphism had a significant association with susceptibility to infection." (PMID 37570285, 2023). "Interestingly, our study revealed that a SNP present in the seed region in miR-15a is predicted to alter its binding with CD163, which could influence immune response to infection." (PMID 33882076, 2021). "Recovery of CD163+ PAMs, together with an increase of Arg-1+ PAMs, was observed at two weeks post-infection which point out that pulmonary macrophages were polarised to M2, but also, an attempt to reconstitute the pulmonary macrophages subpopulations lost during the early stages of the infection." (PMID 33482914, 2021). "The hemoglobin/haptoglobin scavenger receptor CD163 has been identified as the primary receptor for virus entry into the target cells, as genome-edited animals with a knock-out of either the entire CD163 or just the virus interaction site were resistant to infection." (PMID 34679065, 2021). "These genetic and biologic CD163 deficiencies did not exacerbate local infection." (PMID 33004694, 2020). "Gene-edited pigs lacking CD163 were fully susceptible to infection by ASFV." (PMID 32515659, 2020). "Moreover, the treatment of PAMs with the recombinantly expressed CD163 SRCR1-4 could significantly inhibit both PRRSV-1 and PRRSV-2 infections via competitive binding for MYH9 with the endogenous CD163." (PMID 31447818, 2019). "Considering that CD163 and CD169 expression can be induced by IL-10 and IFN-γ respectively, and that IL-10 treatment increases PRRSV infectivity while IFN-γ decreases it, the role of these cytokine in the modulation of macrophage susceptibility to infection requires further investigation." (PMID 31442273, 2019). "Consistent with the membrane CD163 expression, our results show increased levels of sCD163 in ATB patients, which were particularly higher in PE than in plasma, suggesting that CD163+ monocytes might migrate to the site of infection in order to play an immunomodulatory role." (PMID 31779590, 2019). "Also, none of the CD163 SNPs associated to PRRSv risk infection were differentially expressed between SV and LV animals." (PMID 29448955, 2018).